KLRB1 (killer cell lectin like receptor B1)
Diseases named in the same sentence as KLRB1 in open-access papers (continued):
Sharing a sentence is not in itself a finding about the gene and the disease.
ischemic heart disease (1 paper, 2020). "It is noteworthy that increases in MAIT cells are associated with Juvenile Type 1 Diabetes and polymorphisms in KLRB1 have been associated with ischemic heart disease, and differential transcription of KLRB1 has been reported in DM2 and coronary artery disease." (PMID 31888951, 2020).
leiomyosarcoma (1 paper, 2022). An uncommon, aggressive malignant smooth muscle neoplasm, usually occurring in post-menopausal women. "Several studies found that it had a possible prognostic value for good survival in non-uterine leiomyosarcoma and BC, which was consistent with our results that KLRB1 had a protective function in BC." (PMID 35656090, 2022).
leukoplakia (1 paper, 2021). A white patch or plaque on a mucous membrane that cannot be characterized clinically or pathologically as any other disease. "In addition, CYLD, CARD11, TCF7, CCR7, KLRB1, CD28, and ICOS were other significantly highly expressed genes among the proliferative leukoplakia subgroup (log2 fold changes, 0.65–3.51; all Padj = 0.001)." (PMID 36860910, 2021).
metastatic tumors (1 paper, 2024). "Although the expression of KLRB1 was lower in metastatic tumors, the difference was notstatistically significant." (PMID 39507529, 2024).
morbid obesity (1 paper, 2020). An excess of body weight, normally defined as an individual with a body mass index greater than 35 or a body weight greater than one hundred percent of ideal body weight. "The strongest associations occurred between the NEGR1 and KLRB1 gene and obesity and morbid obesity and the NEGR1 gene and abnormal glucose." (PMID 31888951, 2020).
Obesity (1 paper, 2020). Accumulation of substantial excess body fat. "We also observed polymorphisms in KLRB1 correlate with a decrease of odds in extreme obesity risk." (PMID 31888951, 2020). "Our extreme obesity vs. non-obese study also identified two new genes, PFKFB3 and KLRB1, that are not yet found to be significantly associated to BMI." (PMID 31888951, 2020).
renal carcinoma (1 paper, 2023). A carcinoma arising from the epithelium of the renal parenchyma or the renal pelvis. "Higher KLRB1 expression was linked to a lower survival rate only in renal carcinoma, while all of the others showed a better prognosis." (PMID 37520246, 2023).
seminoma (1 paper, 2024). A radiosensitive malignant germ cell tumor found in the testis (especially undescended), and extragonadal sites (anterior mediastinum and pineal gland). "Compared with other TCGA primary diagnosis types, KLRB1 was significantly enriched in the Seminoma type in the TCGA databases." (PMID 38608099, 2024). "The receiver-operating characteristic curve was performed to evaluate the expression specificity of KLRB1 in the Seminoma type of TGCT." (PMID 38608099, 2024). "In our study, we showed that KLRB1 was upregulated in tumor tissues, especially in seminomas, and that elevated KLRB1 expression correlated with adverse clinicopathological features of TGCT." (PMID 38608099, 2024). "In summary, our study demonstrated that KLRB1 was significantly highly expressed in TGCT, especially in seminomas." (PMID 38608099, 2024).
tumor (160 papers, 2005 to 2026). "Preliminary evidence suggests that KLRB1 is associated with changes in the tumor immune microenvironment of LUAD." (PMID 38782996, 2024). "Our analysis revealed associations between KLRB1 expression levels and patient age, tumor status, and tumor staging." (PMID 38914941, 2024). "The expression of KLRB1 depicted a positive association with patient age, gender, tumor size, and tumor stage." (PMID 37351109, 2023). "In this study, we found that decreased KLRB1 levels were associated with lower stromal score, immune score, and tumor purity, as well as lower levels of immune cells such as T cells, cytotoxic cells, B cells, dendritic cells, and natural killer cells." (PMID 37988189, 2023). "For example, the expression of KLRB1 inhibits the cytotoxicity of natural killer cells (NK) and is associated with superior outcome, largely reflect tumor-associated leukocytes." (PMID 36869083, 2023). "In a meta-analysis of expression signatures from diverse tumor samples, expression of KLRB1 (encoding CD161) by tumor-infiltrating leukocytes was identified as the most favorable prognosis marker across 39 malignancies." (PMID 36463401, 2023). "Specifically, this correlation was observed in patients with BRCA and its subtypes (basal, HER2, and luminal), where reduced KLRB1 expression levels were linked to tumor purity, B cells, CD8+ T cells, CD4+ T cells, neutrophils, and dendritic cells." (PMID 37988189, 2023). "Based on the estimate algorithm, it was determined that KLRB1 was associated with changes in the tumor microenvironment (TME) and a better prognosis marker of hepatocellular carcinoma." (PMID 37520246, 2023). "The association of KLRB1 with the tumor microenvironment of BC highlights that it can be utilized as a promising prognostic marker and therapeutic target." (PMID 37351109, 2023). "Recently, KLRB1 has become an increasing focus in tumor research as it has been associated with tumor progression." (PMID 37988189, 2023). "They described the potential effectors of anti-tumor immunity in a population of cytotoxic TILs expressing several natural killer (NK) cell genes, including the CD161-encoding gene KLRB1." (PMID 35406398, 2022). "For instance, As a surface marker on several T cell subsets and NK cells, killer cell lectin-like receptor subfamily B member 1 (KLRB1) encodes CD161 and reflects tumor-associated leukocytes." (PMID 35443644, 2022). "By a-CGH analysis on tumor DNA at progression, we found the loss 12p13.31, containing KLRB1 gene, the loss 16p11.2 containing MAPK3 gene, and the loss 16q11.2–q24.3, containing FANCA gene." (PMID 35742955, 2022). "CD161, encoded by killer cell lectin-like receptor B1 gene, is a newly reported candidate inhibitor of tumour-infiltrating T cells." (PMID 34305920, 2021). "Consistently, the expression of KLRB1 (encoding CD161) has been shown to reflect tumor-associated leukocytes, while CD161 is generally regarded as a marker of NKT cells." (PMID 33164640, 2020). "Additionally, KLRB1 expression was linked to tumor purity, stromal, immune, and estimate scores, the levels of immune cells including B cells, CD8+ T cells, and CD4+ T cells, and immune cell markers in LUAD." (PMID 38782996, 2024). "Low expression of KLRB1 could lead to high cytokine production, and IL-6 was mostly produced by tumor cells as well as tumor-associated fibroblasts." (PMID 37520246, 2023). "Recent research found that expressions of favorably prognostic genes, including KLRB1 (encoding CD161), largely reflect tumor-associated leukocytes, indicating that KLRB1 could be a great break point for the following studies to elucidate the effects of IDD on body immunity." (PMID 41023110, 2025). "Spatial analysis further demonstrated KLRB1 enrichment in the tumor stroma, correlating with CD8+ T cell and M1 macrophage infiltration, and an enhanced response to immunotherapy." (PMID 40612672, 2025).
tumor (continued). "Genetic inactivation of KLRB1 or antibody-mediated blockade of CD161 enhances T-cell cytotoxicity against tumor cells." (PMID 41472734, 2025). "To investigate the role of KLRB1 in the tumor immune microenvironment, we examined its correlation with immune cell infiltration." (PMID 40612672, 2025). "Several genes were similarly down-regulated in all T-LGLL, somewhat less markedly in STAT3-mutated cases, e.g. cluster 2 (149 genes, including key receptors like IL23R and KLRB1) and cluster 8 (46 genes, including tumor suppressors like BEND5 and TCEA3)." (PMID 40721648, 2025). "CD161, encoded by the KLRB1 gene, is recognized as a significant inhibitory receptor on NK and tumour‐infiltrating T cells." (PMID 40000397, 2025). "High KLRB1 expression in CD8+ T cells is associated with improved cytotoxicity and more robust proliferation, enhancing their tumor cell-killing ability." (PMID 40534863, 2025). "Its ligand, lectin-like transcript 1 (LLT1), expressed in various tumors, interacts with KLRB1 on immune cells, thereby modulating the immune milieu within tumor microenvironments." (PMID 38914941, 2024). "To further understand the involvement of KLRB1 in the process of tumor immunogenic cancer cell death, we tested the effect of KLRB1 activation on immune pathways and cytokine profiles." (PMID 38608099, 2024). "Multivariate regression analysis further suggested that tumor number, tumor size, BCLC stage, and the expression of KLRB1 on CD8+ T cells and NK cells were independent risk factors for predicting patient prognosis." (PMID 38914941, 2024). "KLRB1 was highly positively correlated with natural killer cell activation in immune response and positively correlated with tumor-infiltrating immune cells." (PMID 38608099, 2024). "Reduced KLRB1 expression in LUAD was found to positively correlate with tumor size, distant metastasis, pathological stage, age, overall survival, diagnostic value, and disease-specific survival in patients with LUAD (P < 0.05)." (PMID 38782996, 2024). "The clinical significance and biological functions of KLRB1 were explored using the TCGA dataset, and we analyzed the correlation of the KLRB1 gene with tumor immunity and infiltrating immune cells using gene set variation analysis and the TIMER database." (PMID 38608099, 2024). "The analysis identified KLRB1 was significantly upregulated in tumor tissues with the corresponding normal tissues as controls (P < .05)." (PMID 38608099, 2024). "Results demonstrated that patients with high KLRB1 expression in tumor tissue exhibited significantly better prognoses compared to those with low KLRB1 expression." (PMID 38914941, 2024). "In the subsequent analysis, we examined the prognostic value of KLRB1 expression on CD8 T cells and NK cells within the low-risk subgroup of HCC patients (defined as AFP < 400 ng/mL, single tumor, tumor size < 5 cm and BCLC 0 + A)." (PMID 38914941, 2024). "KLRB1 was highly correlated with natural killer cell activation in the immune response and correlated with the level of immune infiltration of tumor cells." (PMID 38608099, 2024). "Analysis of the LUAD tissue data obtained from the TCGA database revealed that the expression level of KLRB1 was found to be significantly correlated with changes in the tumor immune microenvironment indicated via the stromal, immune, and estimate scores." (PMID 38782996, 2024). "Low KLRB1 expression was considered an independent prognostic biomarker and played an important role in the tumor immune microenvironment of BC patients." (PMID 37520246, 2023). "KLRB1 expression levels correlated with tumor purity in BC (p = 2.66e−88, r = − 0.574), as well as with luminal type (p = 2.35e−42, r = − 0.538), HER2-enriched (p = 2.22e−05, r = − 0.522), and basal-like (p = 2.39e−17, r = − 0.658) BC." (PMID 37520246, 2023).
tumor (continued). "GSEA also showed that IL-6 was upregulated when KLRB1 was downregulated, and IL-6 played an important role in tumor proliferation, metastasis, and chemotherapy resistance." (PMID 37520246, 2023). "Next, to explore the possible mechanisms relative to the involvement of KLRB1 in tumor immunity, we determined its biological functions using GO and the KEGG pathway enrichment for 33 cancer types through GSEA." (PMID 35028320, 2022). "To further study the effects of KLRB1 on tumor immunity, we analyzed the correlation between KLRB1 expression and four immune indicators (cytolytic activity, HLA expression, IFN response, and TILs)." (PMID 35028320, 2022). "A good prognosis rate is observed in those cancer patients where KLRB1 is highly upregulated as infiltration of immune cells at tumor site and sensitivity to chemotherapy is KLRB1-dependent in many cancer types." (PMID 35757002, 2022). "It is noteworthy that the most significant differences occurred between the first and second stages, and except for the positive correlation in STAD, the expression of KLRB1 decreased with increasing tumor stages." (PMID 35028320, 2022). "Our research initially revealed the critical role of KLRB1 in predicting the prognosis of patients and tumor immunity, data which can be used as a reference for immunotherapy new targets and as a potential choice for clinical treatment options." (PMID 35028320, 2022). "CD161 encoded by KLRB1 was recently identified as a novel immune checkpoint molecule, and blocking the CD161-CLEC2D pathway strongly enhanced T cell killing against tumor cells and reduced T cell exhaustion." (PMID 36358600, 2022). "Our study also found that the higher the tumor stage, the lower the KLRB1 expression level in LUAD, SKCM, THCA, and TGCT." (PMID 35028320, 2022). "KLRB1 expression was inhibited in tumor tissues, and it potentiated be a prognostic biomarker in carcinoma." (PMID 35233733, 2022). "First, we evaluated the ability of KLRB1 to predict tumor immune characteristics, including immune score and cytolytic activity, and compared it with the TMB and glycolytic activity." (PMID 35028320, 2022). "We identified significant differences in the expression of the KLRB1 gene between normal and tumor specimens in 15 cancers." (PMID 35028320, 2022). "The inactivation of KLRB1 or antibody-mediated CD161 blockade resulted in increased T-cell cytotoxicity against tumor cells in vitro and an enhanced response in vivo." (PMID 35406398, 2022). "Cancer patients with higher expression of KLRB1 had higher levels of T cells and B cells infiltrated in the tumor microenvironment." (PMID 35028320, 2022). "We verified the differences in KLRB1 expression between normal and tumor samples in the GEO database." (PMID 35028320, 2022). "Mathewson and colleagues further identified KLRB1 as an inhibitory receptor for tumor-specific T cells." (PMID 36532059, 2022). "We explored the potential molecular mechanism of KLRB1 in clinical prognosis and tumor immunity from the aspects of gene expression, survival status, clinical phenotype, immune infiltration, immunotherapy response, and chemotherapeutic drug sensitivity." (PMID 35028320, 2022). "Our study will provide a better understanding of the molecular mechanisms involving KLRB1 in tumorigenesis and tumor development and provides a rationale for future immunotherapy and precision medicine." (PMID 35028320, 2022). "NKG7, KLRD1, and KLRB1 are marker genes of T cells and NK cells, which is in line with the fact that the proportions of T and NK cells in tumor samples were significantly smaller than those in paracancerous tissues." (PMID 35967424, 2022). "The expression of KLRB1 is able to influence tumor immune cell infiltration and chemotherapeutic drug sensitivity." (PMID 35992798, 2022). "In contrast, KLRB1’s expression intensity and quantity in normal tissue was higher than that in the tumor tissue." (PMID 33271935, 2020).
tumor (continued). "Conversely, HPV- tumors upregulated CLEC2C and CLEC2D ligands on tumor cell surfaces, engaging the inhibitory receptor KLRB1 on NK cells; this CLEC2-KLRB1 axis correlated with suppressed NK activity and poorer prognosis, and was confirmed at the protein level by IHC." (PMID 41827778, 2026). "The interaction between KLRB1 (encoding CD161) and its ligand CLEC2D modulates the activity of NK cells and T cells, potentially suppressing their cytotoxic functions under certain conditions, thereby facilitating tumor immune evasion." (PMID 40891683, 2025). "Regarding KLRB1, our findings align with those of Jiu-Ling Chen and other researchers, who discovered that KLRB1 was a tumor suppressor gene suggestive of a better prognosis, and that KLRB1 expression was positively correlated with the level of CTLs, B cells and DCs." (PMID 39507529, 2024). "Conversely, other studies have also indicated that KLRB1 may diminish T cell-mediated cytotoxicity and induce NK cell dysfunction, contributing to tumor progression." (PMID 39507529, 2024). "Compared with the adjacent tissues, CD163L1 and KLRB1 mRNA are downregulated in tumor tissues." (PMID 39202452, 2024). "Finally, we verified the association between key NKRGs, KLRB1 and CCND2, and tumor-infiltrating NK cells by combining spatial transcriptomics and IHC assays based on BRCA tissue specimens." (PMID 39507529, 2024). "The protein expression level of KLRB1 in TGCT tumor tissues was higher than that in normal tissues." (PMID 38608099, 2024). "Furthermore, data analysis in the TIMER database revealed that the downregulation of KLRB1 expression was significantly positively correlated with tumor purity, and the levels of B cells, CD8+ T cells, CD4+ T cells, macrophages, neutrophils, and DC." (PMID 38782996, 2024). "Therefore, we analyzed single-cell sequencing data of HCC tissues to further investigate the expression patterns of KLRB1 within tumor tissues." (PMID 38914941, 2024). "While some suggest a correlation between high KLRB1 expression in tumors and poorer patient prognosis, others propose that KLRB1 may enhance the anti-tumor capabilities of immune cells, potentially improving patient outcomes." (PMID 38914941, 2024). "The reason for this contradiction may be the cellular heterogeneity of KLRB1 expression, whose functions in tumor and immune cells may differ." (PMID 39507529, 2024). "Cluster3 of both subsets (which we refer to as NK-innate-likeCD28− and CD28+, respectively), represented in peripheral blood and reduced at the tumor site, were characterized by the expression of NK-like markers KLRB1, KLRC3, and KIR2DL1, along with IKZF2 and ZBTB16 (PLZF)." (PMID 37898752, 2023). "Furthermore, KLRB1 expression levels are significantly correlated with tumor purity, immune infiltration, and immunotherapy-related markers such as PDCD1, CD274, and CTLA4." (PMID 37988189, 2023). "Therefore, when KLRB1 expression was low, tumor cell apoptosis was inhibited and the prognosis, as well as survival, was poor." (PMID 37520246, 2023). "Moreover, the study also indicated that decreased KLRB1 expression correlated with tumor purity, immune score, and immune cell infiltration (B cells, CD8+ T cells, CD4+ T cells, neutrophils, dendritic cells, among others), cell markers, and immunotherapy." (PMID 37988189, 2023). "In this study, identifying differentially expressed genes (DEGs) for stromal and immune components in cases of BC revealed that KLRB1 could be a potential marker affecting the tumor microenvironment of BC." (PMID 37351109, 2023). "Therefore, the up-regulated key TME-related genes SLC27A2, KLRB1, IGKV1OR2-108 and IGHV1-12 in the low-risk score group inhibit tumor progression by affecting the secretion of neutrophils, NK cells and immunoglobulin." (PMID 36869083, 2023).